ITGB1 (integrin subunit beta 1)
Diseases named in the same sentence as ITGB1 in open-access papers (continued):
Sharing a sentence is not in itself a finding about the gene and the disease.
tumor (continued). "Our previous studies showed that certain integrins are controlled directly by tumor-suppressive miRNAs (e.g., miR-29-family, miR-150, and miR-199a) and that the activation of signaling mediated by ITGA3/ITGB1 and ITGA6 enhances the aggressiveness of HNSCC." (PMID 34576110, 2021). "Among the integrin β‐subunits, ITGB1, ITGB2, ITGB4, ITGB5, ITGB6, ITGB7, and ITGB8 were highly expressed in tumour tissues compared with normal tissues." (PMID 34709754, 2021). "In conclusion, ALDH3B2 promotes tumor proliferation and metastasis in CCA by regulating the expression of ITGB1 and upregulating its downstream signaling pathway." (PMID 34907179, 2021). "As expected, integrins interacting with ECM components are expressed in a cell‐type‐selective fashion, such as ITGA4, ITGAL and ITGB7 by immune cells, while tumour and stromal cells strongly expressed ITGA3, ITGAV and ITGB1/4/5/6/8." (PMID 34841720, 2021). "Since miR-134 targets and inactivates KRAS, Nanog mRNA, HNF4α, EGFR, ITGB1, and FOXM1, it also inhibits tumor invasion and metastasis." (PMID 33331954, 2021). "The protein levels of LIMK1, p-cofilin, cofilin, p-CREB, CREB, MMP2, ITGB1, and COL1A1 in mouse tumor tissues were consistent with the metastatic potential of the tumor in mice." (PMID 34079084, 2021). "Key TGFB activators include integrin proteins, 4 of which (ITGA2, ITGA3, ITGB1, ITGB3) displayed increased expression in the HCC tumor cells (Log2 fold change = −6.16, −5.56, −2.32, and −4.35, respectively)." (PMID 33995488, 2021). "Both ITGB1 and ITGB3 have been demonstrated to mediate tumor growth and promote tumor stemness in several tumor types." (PMID 34758833, 2021). "In the present study, for the first time, we examined the influence and the mechanisms of action of ITGB1 in both patient-derived primary HCC cells and primary tumor cell-derived xenograft model." (PMID 34977001, 2021). "To test this, we performed an identical CRISPR screen in vitro, where ITGB1, FERMT1, and CD151 proved less important for tumor growth than in vivo." (PMID 32579974, 2020). "Our recent study of PDAC revealed that the tumor-suppressive miR-124-3p directly regulates ITGA3 and ITGB1 expression, and aberrant expressions of these integrins were closely involved in PDAC molecular pathogenesis." (PMID 32899691, 2020). "We previously observed that in comparison to primary tumor cells, CTCs were more migratory and expressed greater levels of FN1, as well as its downstream effectors ITGB1 and SLUG." (PMID 32630254, 2020). "In our study, to our surprise, we found that some ligands and receptors were highly expressed in both tumor cells and T cells, such as collagen and integrin family genes, such as COL1A1 and ITGB1." (PMID 32549766, 2020). "We investigated the abilities of PODXL, BCL7B, ARHGEF4, and ITGB1 to predict prognosis in PDAC in comparison with UICC TNM stage and tumor size." (PMID 31166991, 2019). "We examined the prognostic value of ITGB1 expression in subgroups stratified by UICC TNM stage, age, gender, tumor size, differentiation grade, lymphatic invasion, venous invasion, and intrapancreatic nerve invasion." (PMID 31166991, 2019). "To evaluate clinical relevance, we examined these genes in a human public dataset and found that ITGB1 and KRT6B expression in BC patient tumor samples are positively correlated with tumor grade." (PMID 31092844, 2019). "Those genes reportedly involved in tumor cell adhesion, gap junction and ECM, such as CHD1, Cx26, Cx43, Cx45, COL1A1, FN1, LOX, ITGB1 and LAMA4, were also up-regulated following 3D cultures." (PMID 26055407, 2015). "MicroRNA-134, the candidate tumor metastasis suppressor, is often downregulated in HCC and significantly inhibited invasion and metastasis by targeting the ITGB1 pathway in HCC." (PMID 24498348, 2014). "Similarly, proliferative monocytes/macrophages engaged stromal cells via ITGB1 while activating mast cells through SPP1-CD44 interactions, which promote tumor stemness and immunosuppression." (PMID 40895540, 2025).
tumor (continued). "rTAM also expressed distinct integrin transcripts, including Itga6, Itgb1, and Itgb5, which bind ECM components including laminin and collagen, and may facilitate interaction at the tumour-normal interface." (PMID 40523200, 2025). "As a curious side note, ITGA2 and ITGB1 assays with AAL and UEA lectins were significantly associated with cardiovascular disease in adjacent macroscopically normal tissue, but not in tumor tissue." (PMID 40287842, 2025). "Additionally, azvudine regulated the interactions from other tumor immune cells to CD4+ T and CD8+ T cells through ligand‒receptor pairs such as COL1A2‒(ITGA1 + ITGB1), CCL4‒CCR5, CCL6‒CCR2, and CXCL16‒CXCR6." (PMID 39819859, 2025). "Across both tumor clusters, MDK–(ITGA4+ITGB1) and MIF–(CD74+CXCR4) emerged as prominent axes." (PMID 40948762, 2025). "Co-culture experiments with ITGA5-knockdown tumor cells (shITGA5, shITGA5/ITGB1) in a non-contact system or treatment with exosomes derived from these cells showed a significant reduction in HPMC migration." (PMID 40770810, 2025). "Notably, the integrin and neural-signal-related receptors, such as ITGB1, ITGA3, and ITGA5, are bound to numerous ligands between tumor regions and normal regions, suggesting its critical impact on tumor invasion." (PMID 41147013, 2025). "As ECM stiffness generally regulates tumor progression through its receptors, we systematically screened several common ECM-sensing receptors (ITGB1, CD44, Piezo1, Piezo2, YAP1, Syndecan1, and DDR1) via siRNA knockdown, and confirmed the knockdown efficiency by conducting qRT-PCR analyses." (PMID 40685383, 2025). "Our observations further indicate that Tip-like ECs may actively respond to PARs signaling cues from Malignant Cluster01 tumor cells, particularly serving as receivers via the MDK-(ITGA6+ITGB1) ligand-receptor pairs." (PMID 39944338, 2025). "Reduced miR-192-5p-mediated repression of ITGB1 may amplify these signaling cascades, leading to increased ECM stiffness and aggressive tumor phenotypes." (PMID 41294900, 2025). "ITGB1 and ITGA4 are drivers of heterotypic T cell clustering with tumor cells." (PMID 40955669, 2025). "Additionally, in cases with a poor prognosis, HIF1A-driven pathways, such as PI3K/AKT, TNF-α, and Wnt, promote tumour proliferation and survival by metabolic reprogramming, as well as upregulation of metastasis-promoting genes such as MMP1, TWIST2, and ITGB1." (PMID 41007296, 2025). "ITGB1 is related to stemness and coexpressed with stem cell markers such as OCT4 and CD44 in tumor cells, whereas its prognostic role remains unclear." (PMID 40287842, 2025). "Additionally, TENASCIN was frequently observed in the HAS group, with tumor cells in this group interacting with other cells, including tumor cells themselves, via TNC - SDC1/SDC4 or TNC - ITGA8_ITGB1/ITGAV_ITGB6." (PMID 39267750, 2024). "Additionally, Midkine (MDK) released from tumour cells interacted with SDC4, SDC1, NCL, ITGA4, ITGA6 and ITGB1 on immune cluster." (PMID 39187937, 2024). "Notably, these markers have previously been linked to different cell types, including endothelial cells (CD44, ENG, F3, MCAM, and ITGB1), immune cells (CD14, CD44, CSPG4, ENG, HLA-DR/DP/DQ), and neuronal cells (NCAM1), as well as astrocytes and tumor cells." (PMID 39594703, 2024). "Moreover, CAF2 was predicted to interact with tumor endothelial cells (TECs) including tip cell and venous TECs via the ANGPT2-(ITGA5 + ITGB1) and PGF-VEGFR1 axes, suggesting a role in promoting endothelial cell proliferation and migration." (PMID 39093451, 2024). "Notably, H4C1, EGFR, and ITGB1 maintained their prominence in terms of presentation levels across subpopulations stratified by HPV status and tumor stage." (PMID 39136024, 2024).
tumor (continued). "Previous studies have demonstrated a strong correlation between a high immune/stromal/ESTIMATE score and a poor prognosis and the advancement of tumor grade in LGG, which suggests that ITGB1 also contributes to the progression of cancer by boosting stromal and immune cell infiltration in LGG." (PMID 38402311, 2024). "To validate ITGB1 as a key mediator of SCLC migration and invasion, we carried out an in vivo approach with different routes of tumor cell injection, either orthotopically into the lungs and i.v. to explore ITGB1-KO effects on intra- and extravasation capacity of tumor cells." (PMID 38775153, 2024). "In recent years, various studies have reported that ITGB1 is involved in ECM remodeling and that tumor microenvironment (TME) is rich in ECM components such as collagen, fibronectin, and laminin, thereby providing a beneficial microenvironment for tumor metastasis." (PMID 38279122, 2024). "The analysis suggested that TECs might promote tumor growth and progression through the interaction of COL4A1/COL4A2 with their partner receptors (ITGAV + ITGB8 and ITGA3 + ITGB1) on epithelial cells." (PMID 39093451, 2024). "In the positive‐ITGB1 expression group, IL‐10 expression was detected in 80.6% (25/31) of tumor cells, whereas in the negative‐ITGB1 expression group, only 28.6% (6/21) of tumor cells showed IL‐10 expression (p < 0.001)." (PMID 35864742, 2023). "Patients with low ITGB1 expression exhibited a significantly high immunotherapy response ratio according to an analysis of tumor immune dysfunction and exclusion (TIDE), which may indicate that ITGB1 is a potential predictor of immunotherapy efficacy." (PMID 35864742, 2023). "Furthermore, exogenous TGFβ1 also increased the levels of these three subunits in neutrophils, suggesting that tumor cells up-regulate ITGA6, ITGB1 and ITGB4 in neutrophils through TGFβ1 regulation." (PMID 37056931, 2023). "Since integrins are important components that mediate the communications between tumor cells and ECM proteins, and after stimulation by ECM proteins, ITGB1 can activate multiple signaling pathways such as FAK and Src to recruit various proteins to form focal adhesions and promote cell migration." (PMID 36997926, 2023). "Furthermore, according to these 7 key genes (ABCB1, CAP1, EGFR, ITGB1, MAPK1, PPARG, SNCA), we plotted the KM curves to show the survival state of high and low expression groups in tumor samples from the TCGA-PAAD dataset." (PMID 37857015, 2023). "The high expression of the ITGB1 protein in tumor cells is reported to be 32.4%, but no clear threshold is known for the high and low expression of ITGB1 in cancer tissues." (PMID 35648752, 2022). "Additionally, we also observed an up-regulation of the Integrin Subunit Beta 1 (ITGB1), a protein involved in the vasculogenic mimicry, an alternative tumor mechanism of vessel-like structure formation." (PMID 35884472, 2022). "Furthermore, in the in vivo experiment, we detected the expression of relevant molecules in tumour tissues, including KLF14, ITGB1, p-AKT (a key molecule in the PI3K/AKT signalling pathway), and cleaved caspase-3 (an apoptosis marker)." (PMID 35570248, 2022). "We also found that Cancer Cells interact with ITGB1, highly expressed in multiple cells such as Fibroblasts, Endothelial Cells, and Basal Cells, through angiogenesis signal molecules (VEGFA) to stimulate tumor growth and metastasis." (PMID 36401283, 2022). "Tumor cell-secreted extracellular matrix molecule such as collagen (COL4A1) can bind to adhesion receptors broadly expressed on many cell types, such as integrin receptor ITGB1." (PMID 36028490, 2022). "The rest genes, CD46, CXCL6, GPI, ITGB1, PLA2G6 and TNFSF4, were revealed for the negative association with tumor suppression." (PMID 35832540, 2022). "Notably, the combination of PTX and the ITGB1 inhibitor LDV significantly suppressed tumor growth and prolonged the overall survival of tumor-bearing mice." (PMID 34758833, 2021).
tumor (continued). "Cell adhesion molecules such as ITGA3, CD47, MDK, ITGB1, CD55, and CDH1 show a trend of upregulation with pseudotime, indicating that cell-cell communications play an important role during the evolutionary process of tumor growth and progression." (PMID 35087839, 2021). "Finally, performed qRT-PCR and western blot analysis in Lnc-408-engineered BC cells, we confirmed that MMP2, ITGB1, and COL1A1 exhibited significant and substantial changes in Hs578T, MCF-7 cells, and primary BC tumor cells." (PMID 34079084, 2021). "Both ITGB1 and LGALS1 mediate cell proliferation, migration and tumour progression." (PMID 34403115, 2021). "Thus, our experiments provided evidence that ITGB1 plays an essential role in accelerating HCC cell proliferation, ultimately hastening HCC tumor growth." (PMID 34977001, 2021). "Furthermore, siRNA targeting ITGB1 efficiently alleviated the phosphorylation and protein maturation of MET, which triggers tumor formation and growth." (PMID 34977001, 2021). "This analysis indicated that the counts of ITGA 2, 3, 6, V, and ITGB1 referred to the mRNA expression of PTC tumor cells and were not affected by the presence of lymphocytic or stromal contamination." (PMID 34208249, 2021). "LDV treatment obviously suppressed the activation of ITGB1/NF-κB signaling in tumor tissues, with or without PTX." (PMID 34758833, 2021). "Our study further demonstrated that type I collagen could mediate the activation of ITGB1/BCL9L/β-catenin signaling pathway, leading to the tumor progression and drugs resistance." (PMID 34319913, 2021). "The 3D collagen cultured ITGB1+ tumor cells revealed strengthened tumorigenic capability compared to ITGB1 negative cells or dish cultured cells." (PMID 34319913, 2021). "ITGB1 (also known as CD29) and CD44 are reported as tumor stem cell markers, and the presence of tumor stem cells could affect the drug treatment and subsequent tumor recurrence." (PMID 38650282, 2021). "Lumican (LUM), which also increased with LV-MEIS1 expression (fold-change = 2.88, FDR = 1.79×10−9), is another member of the tumor-suppressive SLRP protein family and has been shown to increase integrin B1 (ITGB1)-mediated adhesion as well as regulate expression of ITGB1." (PMID 32553107, 2020). "After adjustment by tumor purity, we found ITGA1/A5/A8/A11/AD/AV and ITGB1 showed weakly correlation with macrophage markers in OC, ITGA5/A11 and ITGB5 weakly correlated with Treg markers, ITGAD and ITGB6 showed weakly correlation with natural killer cells markers." (PMID 32765584, 2020). "PODXL, BCL7B, ARHGEF4, ITGB1, or tumor size were not included in the final model of the multivariate analysis." (PMID 31166991, 2019). "ITGB1 has been recognized in the processing of metastatic diffusion of tumor cells, and ITGA5 may promote tumor invasion." (PMID 29914539, 2018). "Indeed, integrins gene expression in the clinical ESCC tumor tissues show significant higher levels of integrin α-1 (ITGA1), ITGA2, ITGA5 and ITGB1 mRNA compared to normal tissue from the same patient." (PMID 30241395, 2018). "We found that ITGB1 expression levels were significantly higher in NSCLC tumor specimens compared to non-neoplastic tissues." (PMID 28537888, 2017). "As more invasive cells express more ITGA5 on their surface and secrete EVs with more ITGB1, the role of FN1-α5β1 in the GBM tumour microenvironment should be further delineated as it may offer an attractive therapeutic target." (PMID 27770278, 2017). "Enhanced expression of ITGB1 at the tumor invasion front correlated with the absence of regional lymph node metastasis and the persistence of physiologically polarized expression of ITGB1 was significantly associated with favorable prognosis." (PMID 26898710, 2016).
tumor (continued). "Instead, drug-induction suggested decrease for ITGB1/CD29c and ALDH1B1, while CD24, CD44, CD166, ALDH1A1 and Lgr5 were unchanged as detected by signals from microarrays with pooled tumor RNA from indomethacin-treated patients versus pooled tumor RNA from control patients." (PMID 25340937, 2014). "Interestingly, ITGA2 and ITGB1 assays with AAL and UEA lectins were significantly associated with cardiovascular disease in adjacent macroscopically normal tissue but not in tumor tissue." (PMID 40287842, 2025). "The differential interactome composition indicates a functional shift in EGFR signaling that may drive increased tumor cell adhesion (CD44, ITGB1, FN1), metabolic adaptation (GAPDH, ENO1) and stress response (HSPA4, HSP90AB1), consistent with mechanisms observed in therapy‐resistant CRC phenotypes." (PMID 41319168, 2025). "However, in UCEC, dysregulation of COL1A1, ITGB1, THY1, and PDGFRA may compromise immune function, enabling tumor progression." (PMID 40817072, 2025). "Furthermore, LINC00115 may also promote the malignant properties of tumor cells by sponging miR-607, which affects the expression of integrin subunit beta 1 (ITGB1), a molecule critical in tumor growth and metastasis." (PMID 40056285, 2025). "Moreover, ligands implicated in the interaction between THBD+ macrophages and malignant tumour cells were identified, including SPP1‐(ITGAV+ITGB1) and APP‐CD74, suggesting the potential of THBD+ macrophages to influence malignant tumour cells through diverse ligands." (PMID 38809929, 2024). "Nevertheless, it is mainly other members of the integrin family that can be used as surface markers, such as ITGA6, ITGA7, and use of ITGB1 has not been reported: available studies suggest that its function is focused on regulating the development and progression of tumor CSC." (PMID 38279122, 2024). "Within tumor tissue in the adequate iron group, and more so in tumors from the excess iron diet group, we found there was also significantly greater (p ≤ 0.05) expression of proteins involved in protein degradation (ANPEP, DPP7, ITGB1, PSMA1, PSMA2, PSMA3, and SERPINB1)." (PMID 38732562, 2024). "We found that tumor inflammation cells, fibroblasts cells, and endothelial cells (Astrocytes, cDC, Chondrocytes, Fibroblasts, Hematopoietic stem cells (HSC), Megakaryocytes, Mesangial cells, Monocytes, Neurons, Tregs, Smooth muscle) had a more enrichment in the ITGB1-high group." (PMID 37007126, 2023). "Numerous studies have confirmed that ITGB1 is responsible for FAK activation, integrin ligand adhesion triggers an increase in FAK tyrosine (Tyr) 397 phosphorylation, and FAK has a marked effect on tumor cell survival, migration, invasion, angiogenesis, and metastasis." (PMID 37004120, 2023). "Several tumor initiating and/or promoting pathways including epidermal growth factor (EGF) and vascular endothelial growth factor-mediated signaling pathways activate the RAS-MAP kinase cascade for ITGB1 transcription through downstream AP-1 family transcription factors." (PMID 37398311, 2023). "By focusing on a subset of MF tumor samples (MF17, MF18, MF21, MF24) for which we recently determined the transcriptional profile of the dominant malignant clones (clonotype 1) by scRNA-Seq, we predicted that these interactions occur with ITGB1 on malignant T lymphocytes." (PMID 37669110, 2023). "To further verify whether DNA methylation was responsible for ITGB1 overexpression, we evaluated the methylation status of ITGB1 in 10 paired HCC tumor and corresponding non-malignant tissues using methylation-specific PCR (MSP)." (PMID 34977001, 2021). "Intriguingly, 5-FU monotherapy could not suppress the tumor growth or prolonged survival time of tumor bearing mice, which might be due to the drugs resistance induced by ITGB1." (PMID 34319913, 2021).